TRO (trophinin)
Description:
Could be involved with bystin and tastin in a cell adhesion molecule complex that mediates an initial attachment of the blastocyst to uterine epithelial cells at the time of the embryo implantation. Directly responsible for homophilic cell adhesion.
Synonyms: KIAA1114; MAGED3; MAGE-D3
Tractability: Antibody: its Gene Ontology location is reachable by antibodies, with high confidence. PROTAC: ubiquitination databases record sites on it.
Gene: Protein-coding gene on chromosome X (54,920,462 to 54,931,436, forward strand). Ensembl gene ENSG00000067445.
Subcellular location (Human Protein Atlas): Cell Junctions; Cytosol
Gene Ontology:
Molecular function: protein binding
Biological process: embryo implantation; homophilic cell-cell adhesion; negative regulation of transcription by RNA polymerase II
Cellular component: nucleus; plasma membrane
Homologues: Orthologues: chimpanzee TRO (99% identical), macaque TRO (95% identical), rabbit TRO (80% identical), rat AABR07037520.1 (74% identical), mouse Tro (71% identical), pig TRO (67% identical), zebrafish ndnl2 (6% identical), Drosophila melanogaster MAGE (4% identical). Paralogues in human: MAGED2 (21% identical), MAGED1 (19% identical), MAGED4 (18% identical), MAGED4B (18% identical), MAGEL2 (13% identical), MAGEE1 (10% identical), MAGEB10 (9% identical), MAGEB4 (8% identical), MAGEF1 (8% identical), MAGEB18 (8% identical), MAGEB1 (8% identical), MAGEB3 (8% identical), and 25 more.
Diseases named in the same sentence as TRO in open-access papers:
TRO is named in the same sentence as 15 diseases in open-access papers, as found by Europe PMC text mining. Sharing a sentence is not in itself a finding about the gene and the disease. The quoted sentences say what the papers report.
ovarian carcinoma (3 papers, 2009 to 2018). A malignant neoplasm originating from the surface ovarian epithelium. "The TRO (Trophinin) gene, with one frameshift variant in exon 12 due to SV (GZsv37822), encodes a membrane protein and involved in blastocyst implantation and associated with ovarian cancer." (PMID 29558483, 2018). "Some molecules, such as BRCA1, soluble Fas levels, Death Receptor 4 and TNF receptor 2 (TNFR2), EF24, and trophinin, have been shown to correlate with cisplatin resistance in human ovarian cancer." (PMID 19293794, 2009). "Moreover the silencing of TRO, coding for trophinin, has been related to cisplatin resistance and increased invasiveness of ovarian cancer cells." (PMID 26620706, 2015).
glioma (2 papers, 2014 to 2020). A benign or malignant brain and spinal cord tumor that arises from glial cells (astrocytes, oligodendrocytes, ependymal cells). "This analysis revealed that some MAGEs including MAGED subfamily are overexpressed, while most others including MAGEE1, MAGEE2, MAGEL2, MAGEH1, NDN, and TRO are downregulated in glioma." (PMID 33425727, 2020). "Further, other downregulated T2Ms in glioma, including MAGEE1, MAGEL2, TRO, and NDN also exhibited similar negative correlations with immune cell infiltration in LGG, while in GBM they showed a varying degree of positive correlations with infiltration of different immune cells." (PMID 33425727, 2020).
colon cancer (1 paper, 2023). "Rotenone enhanced the mRNA expression of TRO, a toxic rotenoid compound that inhibited colon cancer cell proliferation, invasion, and migration through the PI3K/AKT pathway and promoted apoptosis." (PMID 37985782, 2023).
Infertility (1 paper, 2012). "Although trophinin null male mice did not exhibit infertility, when we isolated sperm from 4–5 month old trophinin null male mice from twice back-crossed or the second generation of the C57BL/6 strain, we observed that sperm were often immotile (LW and MNF, unpublished observations)." (PMID 23194061, 2012).
liver cancer (1 paper, 2014). An epithelial or non-epithelial malignant neoplasm that arises from the liver. "Here we identified the role of KIAA1114, a full-length translational product of the trophinin gene, as a distinctive marker for TICs in human liver cancer by developing a DNA vaccine-induced monoclonal antibody targeting the putative extracellular domain of KIAA1114." (PMID 24713374, 2014).
male infertility (1 paper, 2012). The inability of the male to effect fertilization of an ovum after a specified period of unprotected intercourse. "However, trophinin gene knockout mice do not show apparent neurological defects or male infertility, leaving trophinin’s role in neuronal or spermatogenic cells elusive." (PMID 23194061, 2012).
metastatic tumors (1 paper, 2014). "Previous studies have suggested that the expression of TROPHININ was frequently observed in patients bearing malignant or metastatic tumors, including testicular germ tumor and adenocarcinomas of colon and lung." (PMID 24713374, 2014).
cancer (3 papers, 2014 to 2024). A tumor composed of atypical neoplastic, often pleomorphic cells that invade other tissues. "PROS1 is highly expressed in Cancer Cells, Endothelial Cells, Fibroblasts, and M1 Macrophages, and; SCGB2A2 is highly expressed in Cancer Cells, Epithelial Cells, and Granulosa, TRO is expressed in Fibroblasts." (PMID 37985782, 2023).
TRO also shares sentences with these, for which no sentence is quoted: tumor (3 papers); hepatocellular carcinoma (2); osteosarcoma (2); adenocarcinoma (1); breast carcinoma (1); cholangiocarcinoma (1); testicular seminoma (1).